CXCR4 (C-X-C motif chemokine receptor 4)
Diseases named in the same sentence as CXCR4 in open-access papers (continued):
Sharing a sentence is not in itself a finding about the gene and the disease.
tumor (continued). "Tumor cells, along with other stromal and immune cells in the TME, secrete chemokines including CCL22, CCL20, and CXCL12, which bind to CCR4, CCR6, and CXCR4 on Tregs and direct their recruitment and activation within the TME." (PMID 41890756, 2026). "Chemokine networks, particularly the CXCL12/CXCR4/CCR7 axis, play a crucial role in guiding tumor cells to their destinations." (PMID 41596524, 2026). "CAR exhibited upregulation of tumor-related chemokine signaling (e.g., CCR5, CXCR4), while SARDS showed pronounced enrichment in vascular inflammation pathways." (PMID 41976030, 2026). "The CXCR4 antagonist WZ811 reduced the viability of MM PCs and cell lines, while tumor microenvironment cells from both MM patients and healthy donors exhibited significant resistance." (PMID 41701357, 2026). "Activation of the C-X-C motif chemokine receptor 4 (CXCR4) by its ligand, C-X-C motif chemokine ligand 12 (CXCL12), drives tumor growth and metastasis." (PMID 41510167, 2026). "Functional studies demonstrate that pharmacologic inhibition of CXCR4 for example, Bortezomib can significantly reduce CTCL cell migration and decrease tumor-cell survival." (PMID 41614909, 2026). "The chemokine receptor CXCR4 and its ligand CXCL12 (SDF-1) constitute a critical axis in tumor biology, influencing tumor cell proliferation, invasion, angiogenesis, and immune evasion." (PMID 41750259, 2026). "Upstream, tumor-stromal interactions may contribute to PDIA6 upregulation, as cancer-associated fibroblast-derived C-X-C motif chemokine ligand 12 (CXCL12) activated C-X-C chemokine receptor 4 (CXCR4)-dependent signal transducer and activator of transcription 3 (STAT3) signaling in vitro." (PMID 42234404, 2026). "Experiments show that changes in CD8+ T‐cell localization are regulated by diurnal CXCR4 expression and TGF‐β–SMAD signaling, allowing for precise spatiotemporal control of tumor immune evasion." (PMID 41257391, 2026). "During MF progression, CXCR4 and CXCL12 expressions increase concomitantly as the disease advances from the plaque to the tumor stage, reinforcing the crucial involvement of this signaling axes in CTCL development and progression." (PMID 41614909, 2026). "It has been established that SDF-1α, through its receptor CXCR4, activates critical signaling pathways (PI3K/Akt, MAPK/ERK, JAK/STAT3) that promote tumor growth, invasion and migration." (PMID 41597220, 2026). "CXCR4-targeted [68Ga]Ga-Pentixafor was highly specific in delineating CXCR4-high cell line-derived xenografts and patient-derived xenografts (PDXs) via positron emission tomography (PET) imaging, with precise tumor-targeting and persistent retention." (PMID 41632105, 2026). "Activated pancreatic stellate cells (PSCs) within the tumor microenvironment secrete CXCL12, the ligand for CXCR4, thereby promoting stemness, epithelial-to-mesenchymal transition (EMT), and chemoresistance in miCSCs." (PMID 41991735, 2026). "This ultimately forms a self-amplifying loop where chemotherapy-induced hypoxia leads to unintentional CXCR4/CXCL12 activation and consequently tumour regrowth." (PMID 41002447, 2025). "Research has also identified markers such as CXCR4 and COX-2 in BCC and SCC, with correlations observed between these markers and tumor invasion depth." (PMID 40959430, 2025). "Conclusively, CAFs promoted PCSC proliferation and tumor growth by enhancing the Wnt/β-catenin and SDF-1/CXCR4 signaling pathways." (PMID 40735647, 2025). "These tumor subtypes cooperatively drive CD8+ T cell exhaustion through the MDK–(ITGA4+ITGB1), MIF–(CD74+CXCR4), and TGF-β signaling pathways." (PMID 40948762, 2025). "IL24 has been shown to suppress tumor invasion and metastasis by modulating matrix metalloproteinase (MMP) expression or SDF-1/CXCR4 signaling axis, while NKG2D enhances the targeting and killing of tumor cells, further reducing their ability to migrate." (PMID 40076725, 2025).
tumor (continued). "Secondly, miR-222 inhibits TAM chemotaxis by targeting C-X-C chemokine receptor type 4 (CXCR4) and C-X-C motif chemokine ligand 12 (CXCL12), which ultimately suppresses tumor growth in vivo." (PMID 41357196, 2025). "Given that CXCR4 acts as the receptor for SDF-1, a potent chemokine integral to tumor progression and growth, we employed AMD3100, a well-established CXCR4 antagonist widely used for HSPC mobilization from the bone marrow." (PMID 40822347, 2025). "For instance, the CXCL12/CXCR4 axis is particularly pivotal in ESCC, where it not only promotes tumor growth but also facilitates lymphatic and vascular invasion." (PMID 40134607, 2025). "An enrichment in the T cell adhesion pathway was further supported by the upregulation of genes regulating T cell chemotaxis and recruitment, including chemokine receptors CXCR4 and CCL5 which enable T cell migration toward tumours." (PMID 41267637, 2025). "Circ-TMX4 acts as a sponge for miR-622, resulting in upregulation of CXCR4, a key mediator of metastasis, thus establishing the ERβ1/circ-TMX4/miR-622/CXCR4 axis as a novel pathway linking ERβ1 to tumor aggressiveness and therapy response." (PMID 40710178, 2025). "Collectively, our data points at CXCR4 and S1P1/5 as initiators of low-grade stimulation that partially desensitizes NK cells to productive stimulation by tumor cells." (PMID 40155684, 2025). "In mice with tumors of TNBC, PVT significantly reduced tumor growth and the expression levels of PTP1B, CXCL12, CXCR4, PI3K, AKT, mTOR and other proteins in TNBC tumor tissue and upregulated the expression of IL-24." (PMID 40076586, 2025). "The CXCL12/CXCR4 axis is pivotal for triggering EMT, which is essential in drug resistance and tumour development in TNBC." (PMID 41002447, 2025). "FAP+ stromal cells have been shown to suppress anti-tumor immunity, and CXCL12 produced by FAP+ CAFs drives T cell exclusion and blunts responses to αCTLA-4/αPD-L1, findings that motivated later CXCR4-blockade combinations." (PMID 40940809, 2025). "Preclinical studies have shown that CXCR4 antagonists, such as AMD3100, in combination with PD-1 inhibitors, can effectively overcome the immunosuppressive tumor microenvironment and enhance antitumor immune responses." (PMID 41002423, 2025). "The results showed that Ga-68-labeled CXCR4 PET/CT successfully localized and quantified CXCR4 expression levels in tumors, providing crucial information about tumor biology." (PMID 39911388, 2025). "In vivo, CAFs promoted CRPC tumor growth and significantly increased the expression of Wnt3a, β-catenin, TCF4, LEF1, SDF-1, and CXCR4, along with an elevated p-GSK-3β/GSK-3β ratio." (PMID 40735647, 2025). "VEGF, TGF-β, CXCR4, Cav-1, Wnt7a, EGFR and EPHA2 enhance vascular formation and influence tumor microenvironment dynamics." (PMID 40486870, 2025). "Attraction of mobilized neutrophils to the tumor site is realized via chemokines CXCL1, CXCL2, CXCL5, CXCL6, and CXCL8 (IL-8) through CXCR1/2 and CXCL12 (SDF-1) and its receptor CXCR4." (PMID 40050933, 2025). "The CXCL12/CXCR4 axis NFBK1 regulates can also promote the infiltration of regulatory T cells (Tregs) and inhibit anti-tumor immunity." (PMID 40666524, 2025). "C-X-C Motif Chemokine Ligand 12 (CXCL12) secreted by CAFs binds to tumor cell CXCR4, thereby activating downstream signaling that enhances cancer stem cell (CSC) drying and invasion, leading to tumor progression and metastasis." (PMID 41346633, 2025). "These nanoparticles were designed to selectively internalize and release the cargo drug into CXCR4+ B-cell NHL showing effective drug delivery and tumor targeting." (PMID 40307933, 2025). "CXCL12 correlated with CD274 (R = 0.369) and PDCD1 (R = 0.288); CXCR4 correlated with CD274 (R = 0.579) and PDCD1 (R = 0.520), suggesting their roles in regulating immune checkpoints and tumor immune escape." (PMID 41142306, 2025).
tumor (continued). "Chemotactic interactions promote attraction and activation of cytotoxic cell subsets, likely promoting anti-tumor activity in the TME of R (pDC GPI → NK AMFR, pDC MIF → NK T CD74/CXCR4, and NK T CCL3L1 → CD8 + T CCR5)." (PMID 41185627, 2025). "Inhibits the CXCL12/CXCR4 signaling axis; reduces the accumulation of M2-TAM; suppresses tumor growth, invasion, and metastasis." (PMID 40109347, 2025). "For example, this pro-tumor effect of CAFs can be mediated in GC by CXCL12 and its receptor CXCR4 released by CAF in an autocrine and paracrine manner, respectively." (PMID 40485724, 2025). "These experiences underscore the need for biomarker-gated eligibility, combination designs (e.g., CXCR4 blockade to disrupt CXCL12-mediated exclusion), and careful on-target/off-tumor safety monitoring when engaging broadly expressed stromal markers." (PMID 40940809, 2025). "In comparison to non-tumor samples, it was observed that the protein levels of TGFβ-1, IL19, CXCR4, BMP1, VCAN, and WNT2 were significantly enhanced in several tumor samples." (PMID 41348904, 2025). "Chemokine receptor engineering (CXCR1, CXCR4, CCR7) improves trafficking and tumor infiltration both in hematological and solid tumors." (PMID 41487532, 2025). "Another key axis is CXCL12/CXCR4, whose activation results in enhanced ERK and PI3K/AKT signaling in tumor cells, directly linking to increased vascular invasion and poor clinical prognosis." (PMID 41445734, 2025). "Fluorescent staining of tumour sections for hypoxia and validated markers in the H22 tumour-carrying mouse model showed that PFH@LSLP enhances anti-tumour effects by reducing hypoxic zones and increasing HIF-1α and CXCR4 expression in PDX HCC tumours." (PMID 40092984, 2025). "CXCR4, a G-protein-coupled receptor, binds specifically to its ligand CXCL12, promoting tumour cell proliferation, metastasis, immune evasion, and stromal remodelling." (PMID 41002447, 2025). "For example, neutrophils and NK cells showed significant interactions with tumour cells through pathways such as MIF‐(CD74 + CXCR4) and ANNEXIN‐(FPR1 + FPR2), which are known to modulate immune responses and tumour progression." (PMID 40099956, 2025). "Cisplatin treatment has been shown to reduce tumour size while also increasing secretion of CXCL12, recruitment of metastasis initiating cells and pro-invasive CXCR4+ macrophages, that promote spontaneous metastasis." (PMID 39982274, 2025). "As CXCR4/SDF-1 is a key signaling axis mediating the interaction between CAFs and tumor cells, several clinical studies targeting CXCR4 have also been carried out." (PMID 40626005, 2025). "According to the results of cell–cell communication analysis among C2, C5, and other clusters, terminal states of tumor-infiltrating CD4+ T cells were specifically enriched in the MIF signal pathway (MIF-CD74+CD44, MIF-CD74+CXCR4)." (PMID 41008548, 2025). "In conclusion, exosome-mediated HIF2A derived from primary tumor activates peritumoral fibroblasts to secrete CXCL12, thus preparing 'soil' enriched with CXCR4+ M2 macrophages for future invasion of cancer cell." (PMID 40756343, 2025). "CXCR4 antagonists disrupt the CXCR4/CXCL12 signaling pathway, thereby enhancing the efficacy of chemotherapy by increasing drug delivery to the tumor and reducing resistance mechanisms driven by hypoxia and stromal interactions." (PMID 40075611, 2025). "M2-polarized HMC3 microglia promoted tumor angiogenesis by releasing exosomal circKIF18A, and circKIF18A bound to its target gene FOXC2 that upregulated ITGB3, CXCR4, and DLL4 expressions and activated PI3K/AKT signaling." (PMID 39781357, 2025). "Focusing on the SSR4+ and SSR4- cell subtypes, SSR4 expression levels were closely related to the interaction patterns that existed between tumor plasma cells as well as other cell subtypes, especially in the MIF/CD74/CXCR4 pathway." (PMID 40066443, 2025).
tumor (continued). "Activation of CXCL12/CXCR4 triggers downstream signaling pathways, including the PI3K/AKT/mTOR and MAPK/ERK cascades, which promote tumor cell proliferation and survival." (PMID 40698080, 2025). "The major chemokine receptors expressed in the NK cell population, including CXCR4, CXCR3, CCR3, CCR5, and CX3CR1, facilitate the distribution of NK cells in response to chemokines present in the tumor microenvironment (TME)." (PMID 41246355, 2025). "Studies have shown that CXCL12/CXCR4 activation leads to downstream STAT3 phosphorylation, promoting transcription of genes related to tumor growth and angiogenesis, such as VEGF, MCL-1, and BCL-XL." (PMID 40607416, 2025). "The hypoxic tumor microenvironment further modulates CXCR4 activity, as HIF-1α drives CXCL12/CXCR4 upregulation under low oxygen conditions." (PMID 40607416, 2025). "Tumor cells can secrete CXCL12, which recruits these immunosuppressive cells into the TME by binding to C-X-C chemokine receptor type 4 (CXCR4) on the surface of immune cells." (PMID 41346580, 2025). "The results showed a pattern in which PECAM1, VWF, CXCR4, and CXCL12 appeared to infiltrate regions of the tumor delineated by HE staining and EPCAM." (PMID 39965034, 2025). "In the tumor microenvironment, CXCL12 secreted by stromal cells like CAFs/PSCs and potentially nerves attracts CXCR4-overexpressing PDAC cells, guiding their migration toward neural structures and facilitating PNI." (PMID 40909268, 2025). "SDF-1 and its receptors, CXCR4 and CXCR7, can promote tumor cell proliferation, survival, angiogenesis, and metastasis." (PMID 40136462, 2025). "CXCR4 is prominently expressed in both primary and metastatic ESCA lesions, enabling tumor cell homing to CXCL12-rich niches such as lymph nodes." (PMID 40134607, 2025). "The CXCR4/CXCL12 axis, for example, has been shown to regulate neutrophil-tumor cell interactions, promoting neutrophil infiltration into tumors and enhancing their pro-angiogenic activities." (PMID 40050933, 2025). "This core network of IL-19, TGFβ-1, CXCR4, BMP1, VCAN, and WNT2 reveals a tight-knit module that regulates tumor aggressiveness, immune evasion, and therapy resistance." (PMID 41348904, 2025). "The results showed that compared to the oe‐NC group, the CXCR4 and CXCL12 protein levels remained unchanged in the tumor tissues of the oe‐NC+M2pep‐Cs NPs/Plerixafor group." (PMID 40536774, 2025). "For instance, a clinical trial for BL‐8040, a CXCR4 inhibitor, in combination with immune checkpoint inhibition, showed improved CTL tumour infiltration, decreased immunosuppressive immune cells, and improved overall PDAC patient survival." (PMID 39931761, 2025). "CXCL12 binds to the CXCR4 and CXCR7 receptors and is involved in many physiological and pathologic processes, including immune response, cell migration and tumor metastasis." (PMID 41376630, 2025). "To visualize the expression of CXCR4 in MOC1 and MOC2 tumor stroma, we performed IHC staining for CXCR4." (PMID 41210695, 2025). "In PCa, hypoxia induces CXCR4 expression via HIF-1α–dependent transcription, enhancing tumour cell chemotaxis toward CXCL12 (SDF-1) secreted by bone marrow stromal cells, a key mechanism promoting bone metastasis." (PMID 40806577, 2025). "On the one hand, tumor cell C1_EGFR+ and C2_STAT1+ directly act on CD8T_GNLY+ through the MDK–(ITGA4+ITGB1) axis and the MIF–(CD74+CXCR4) axis to promote tumor proliferation." (PMID 40948762, 2025). "Chemokine–receptor interactions, such as the CXCL12/CXCR4 and HGF/c-Met axes, play central roles in guiding NSCs to tumor sites." (PMID 41264121, 2025). "Their trafficking and infiltration into solid tumors is frequently suboptimal, although this can be improved by engineering expression of chemokine receptors such as CXCR4, CXCR1, or CXCR2 to match tumor-secreted ligands." (PMID 40941014, 2025).
tumor (continued). "IFN-γ can facilitate tumor metastasis by inducing the expression of ICAM1 and CD13, promoting epithelial-mesenchymal transition (EMT), and stimulating the production of CXCR4 and MUC4." (PMID 40143164, 2025). "Inhibition of CXCR4 disrupts the crosstalk between OS cells and ECM, significantly suppressing tumor cell migration." (PMID 40600065, 2025). "CXCL12, also recognized as stromal cell-derived factor 1 (SDF-1), promotes tumor proliferation and angiogenesis via the CXCL12/CXCR4 pathway." (PMID 40313969, 2025). "Upon binding CXCR4, CXCL12 promotes multiple downstream signalling cascades that can facilitate tumour survival/progression and even resistance." (PMID 41002447, 2025). "Among them, the CXCR4 antagonist mavorixafor enhances CD8+ cell infiltration and decreases immunosuppressive cells in the tumor microenvironment." (PMID 41346591, 2025). "The ligand‐receptor interactions between tumor cells and major immune cell populations were mainly present in the MIF signaling pathway, with the ligand‐receptor pair MIF‐(CD74 + CXCR4) exerting the most significant influence on this pathway." (PMID 40018995, 2025). "C-X-C chemokine receptor type 4 (CXCR4), a chemokine receptor expressed on Tregs and MDSCs for chemokine (C-X-C motif) Ligand 12 (CXCL12), mediates their recruitment into the tumor bed." (PMID 41013723, 2025). "B7-H3 directly interacts with CXCR4 to activate AKT, ERK, and JAK2–STAT3 signaling, enhancing tumor cell motility and invasiveness." (PMID 41225987, 2025). "The upregulated CXCL12/CXCR4 signaling pathway in GBM contributes to an immunosuppressive tumor immune microenvironment (TIME) and tumor progression, with AMD3100 as a CXCR4 inhibitor." (PMID 39866779, 2025). "Macrophages emerged as key regulators, utilizing the CXCL12/CXCR4 axis to recruit CD8+ effector T cells and regulatory T cells (Tregs) into the tumor microenvironment (TME)." (PMID 41347146, 2025). "In a 4T1 BC model, rAd.sT significantly reduced tumor weight, inhibited lung metastasis, and downregulated angiogenesis- and metastasis-related genes such as VEGFA, CXCR-4, and E-cadherin." (PMID 40281554, 2025). "Motixafortide is a synthetic peptide that binds with high affinity to CXCR4, a G protein–coupled receptor, inhibiting the CXCR4–CXCL12 axis and enhancing T-cell infiltration into the tumor microenvironment." (PMID 40572765, 2025). "The CXCR4 antagonist AMD3100 has been shown to impair the immunosuppressive function of these cells and improve anti-tumor immune responses." (PMID 40963620, 2025). "AMD3100 possibly impairs the CXCR4-mediated recruitment and proliferation of CD105+ tumor vessels in the TME, leading to a hypoxic environment and triggering necrosis." (PMID 41210695, 2025). "Conversely, some genes, including CXCR4, KITLG, STAT3, and TNFSF10, were downregulated, suggesting a potential suppression of specific pathways related to tumor proliferation and vascular development." (PMID 39861616, 2025). "Mavorixafor (X4P-001, AMD070) is another orally bioavailable CXCR4 antagonist that enhances CD8+ cell infiltration and decreases immunosuppressive cells in the tumor microenvironment." (PMID 40307933, 2025). "The authors further demonstrated that RhoA suppresses invasion by reducing the expression of the tumor progression chemokines CCR5 and CXCR4." (PMID 40214422, 2025). "Interactions between CXCR4 and its ligand, CXCL12, support tumor growth by enhancing angiogenesis, immune evasion and resistance to therapies, as well as tumor metastasis." (PMID 40227824, 2025). "The CXCL12/CXCR4 axis promotes epithelial-mesenchymal transition (EMT), enhances tumor cell migration and invasion, and facilitates distant metastasis through interactions with the tumor microenvironment." (PMID 40481962, 2025). "Research suggests that Infliximab can suppress H. pylori–induced upregulation of CXCR4 by inhibiting TNF-α signaling, thereby reducing GC cell migration and exhibiting anti-tumor potential." (PMID 41376630, 2025).